TARS2 (threonyl-tRNA synthetase 2, mitochondrial)
Description:
Catalyzes the attachment of threonine to tRNA(Thr) in a two-step reaction: threonine is first activated by ATP to form Thr-AMP and then transferred to the acceptor end of tRNA(Thr). Also edits incorrectly charged tRNA(Thr) via its editing domain.
Synonyms: ThrRS; TARSL1; FLJ12528; COXPD21
Tractability: PROTAC: ubiquitination databases record sites on it; its protein half-life has been measured.
Target class: Enzyme; Ligase
Gene: Protein-coding gene on chromosome 1 (150,487,325 to 150,507,613, forward strand). Ensembl gene ENSG00000143374.
Subcellular location: Mitochondrion matrix
Subcellular location (Human Protein Atlas): Cytosol; Nucleoplasm
Pathways (Reactome):
Metabolism of proteins: Mitochondrial tRNA aminoacylation
Gene Ontology:
Molecular function: aminoacyl-tRNA deacylase activity; protein binding; protein homodimerization activity; threonine-tRNA ligase activity; aminoacyl-tRNA ligase activity; ATP binding; nucleotide binding
Biological process: mitochondrial threonyl-tRNA aminoacylation; threonyl-tRNA aminoacylation; aminoacyl-tRNA metabolism involved in translational fidelity; tRNA aminoacylation; tRNA aminoacylation for protein translation
Cellular component: mitochondrion; cytoplasm; mitochondrial matrix
Genetic constraint (gnomAD): Loss-of-function variants: 63 observed, 102.27 expected, observed/expected ratio (o/e) 0.62, 90% interval 0.5 to 0.76. The upper end of that interval is the gene's LOEUF score, 0.76, which puts it in group 3 of 6, group 1 being the genes least tolerant of losing a copy. Missense variants: 704 observed, 949.57 expected, observed/expected ratio (o/e) 0.74, 90% interval 0.7 to 0.79. Synonymous variants: 359 observed, 373.21 expected, observed/expected ratio (o/e) 0.96, 90% interval 0.88 to 1.05.
Gene-disease validity (ClinGen):
ClinGen rates the evidence that TARS2 causes each of these diseases.
mitochondrial disease (autosomal recessive): Definitive.
Leigh syndrome (autosomal recessive): Limited. A progressive neurological disease defined by specific neuropathological features associating brainstem and basal ganglia lesions.
Homologues: Orthologues: chimpanzee TARS2 (99% identical), macaque TARS2 (97% identical), pig TARS2 (89% identical), rabbit TARS2 (88% identical), dog TARS2 (87% identical), mouse Tars2 (84% identical), rat Tars2 (83% identical), Drosophila melanogaster ThrRS (49% identical), Caenorhabditis elegans tars-1 (47% identical), guinea pig Tars2 (33% identical), Caenorhabditis elegans pars-1 (12% identical). Paralogues in human: TARS3 (53% identical), TARS1 (52% identical), PARS2 (13% identical), MRPL39 (10% identical).
Diseases named in the same sentence as TARS2 in open-access papers:
TARS2 is named in the same sentence as 16 diseases in open-access papers, as found by Europe PMC text mining. Sharing a sentence is not in itself a finding about the gene and the disease. The quoted sentences say what the papers report.
epilepsy (4 papers, 2014 to 2025). A brain disorder characterized by episodes of abnormally increased neuronal discharge resulting in transient episodes of sensory or motor neurological dysfunction, or psychic dysfunction. "In this study, we identified a specific TARS2 variant as a novel cause of NDM, epilepsy and developmental delay highlighting a critical role for TARS2 in the function of β‐cells, and in the CNS." (PMID 39509107, 2025). "Biallelic TARS2 variants cause a mitochondrial encephalopathy (COXPD‐21) characterised by severe hypotonia, epilepsy and developmental delay." (PMID 39509107, 2025). "Biallelic variants in TARS2 are linked to mitochondrial myopathy, SNHL, and epilepsy, all of which are indicative of the profound impact that mitochondrial dysfunction can have on both auditory and neural tissues." (PMID 41191133, 2025).
Mitochondrial Encephalomyopathies (4 papers, 2014 to 2024). "In this study, we reported additional four individuals from three unrelated Chinese families with mitochondrial encephalomyopathy caused by pathogenic variants in TARS2, and described the novel clinical phenotypes and genotypic information." (PMID 39394138, 2024). "TARS2 is located in the mitochondria and participates in protein translation, and mutations in TARS2 cause mitochondrial encephalomyopathies." (PMID 35184682, 2022). "Current research shows that P282L mutation of TARS2 causes mitochondrial encephalomyopathies in humans." (PMID 35184682, 2022). "Mitochondrial encephalomyopathy caused by bi-allelic deleterious variants in TARS2 is rare." (PMID 33153448, 2020).
developmental delay (3 papers, 2018 to 2025). "These diseases display a broad clinical spectrum and may be further complicated with other symptoms such as developmental delay (NARS2, PARS2), pontocerebellar hypoplasia (RARS2), visual impairment (FARS2) psychomotor delay (TARS2) and microcephaly (VARS2)." (PMID 29288497, 2018).
diabetes (2 papers, 2025). "Further studies will be needed to understand how disruption of mitochondrial protein translation by the m.3243A>G variant and variants in NARS2, SARS2, and TARS2 affects the β‐cell, leading to monogenic diabetes." (PMID 40887432, 2025). "Using genome sequencing, we identified a homozygous TARS2 variant, p.(Arg327Gln), in four individuals with neonatal diabetes and additional neurological features." (PMID 39509107, 2025). "We report the identification of a homozygous TARS2 variant, p.(Arg327Gln), in four individuals with diabetes diagnosed up to 1 year of age and neurological disease." (PMID 39509107, 2025). "Three individuals, all diagnosed with diabetes in the first week of life, shared a rare homozygous missense variant, p.(Arg327Gln), in TARS2." (PMID 39509107, 2025). "Further studies are needed to assess whether the TARS2 p.(Arg327Gln) variant causes diabetes through mitochondrial dysfunction, disruption of mTORC1 signalling or both." (PMID 39509107, 2025). "We hypothesise that the TARS2 p.(Arg327Gln) variant results in neonatal diabetes by specifically disrupting TARS2's regulation of the mTORC1 pathway which in turn affects β‐cell survival and function." (PMID 39509107, 2025). "Consistent with this hypothesis, the individual with TARS2‐related disease who had diabetes reported in the literature was also homozygous for a variant in the TARS2301‐381 region." (PMID 39509107, 2025).
mitochondrial encephalopathies (2 papers, 2014 to 2025). "Our study reports the first mutations in the VARS2 and TARS2 genes, which encode two mitochondrial aminoacyl-tRNA synthetases, as causes of clinically distinct, early-onset mitochondrial encephalopathies." (PMID 24827421, 2014).
cholelithiasis (1 paper, 2025). The presence of crystallized deposits forming in the gallbladder or biliary tree, primarily composed of cholesterol, bilirubin, and bile. "Methylation of cg09579323 downregulates TARS2 expression, thereby increasing cholelithiasis risk, suggesting that TARS2 may indirectly regulate bile acid synthesis enzymes by maintaining mitochondrial translation efficiency." (PMID 40958306, 2025). "Methylation of cg09579323 in TARS2 (OR = 1.05, 95% CI = 1.02–1.08) was associated with an increased risk of cholelithiasis, whereas increased TARS2 gene expression (OR = 0.73, 95% CI = 0.62–0.86) was associated with a reduced cholelithiasis risk." (PMID 40958306, 2025). "This study, through multi-omics integrative analysis, provides the first evidence of a causal link between mitochondrial-related genes (LIAS, TARS2, HEBP1, PNKD) and cholelithiasis, and evaluates their potential as viable drug targets." (PMID 40958306, 2025). "This study, using the SMR and HEIDI testing methods, investigated the association of genetically predicted mitochondrial-related gene methylation, gene expression, and cholelithiasis, identifying 4 potential drug targets for cholelithiasis: TARS2, LIAS, HEBP1, and PNKD." (PMID 40958306, 2025). "Although no colocalization evidence for TARS2 and cholelithiasis was found in this study (Tier 2 gene), reduced expression of TARS2 was associated with a lower risk of cholelithiasis (OR = 0.73, 95% CI = 0.62–0.86)." (PMID 40958306, 2025). "Through multi-omics integration, we have constructed for the first time a causal pathway linking mitochondrial-related genes, metabolic pathways, and cholelithiasis, providing theoretical support for personalized therapies targeting the genes LIAS, TARS2, HEBP1, and PNKD." (PMID 40958306, 2025).
COVID-19 (1 paper, 2021). A disease caused by infection with severe acute respiratory syndrome coronavirus 2. "More importantly, this work identifies TARS2, HARS2, and EARS2 as potential key factors involved in COVID-19." (PMID 35153822, 2021). "Although there has been no study to report the tRNA-like elements regulated by TARS2, HARS2 or EARS2, the investigation of the aaRSs-mediated control of viruses or host mRNAs, as well as the function of tRNA-like structures will reveal novel molecular mechanisms for COVID-19." (PMID 35153822, 2021).
tumor (4 papers, 2021 to 2024). "We hypothesized that TARS2 may serve as a clinical diagnostic and prognostic marker and may be involved in tumor progression." (PMID 35184682, 2022). "Western blotting confirmed the high expression of TARS2 in five tumor tissues of lung adenocarcinoma patients." (PMID 35184682, 2022). "The referred significant proteins in the DNA repair panel, especially AARS1 and TARS2, were significantly and highly expressed in the Hot tumor cluster, and were overrepresented in the tumor tissue both in the D and G subtypes, implying their potential value in the clinic strategy." (PMID 36991000, 2023). "Finally, the effect of TARS2 on tumor growth was examined using a xenotransplanted tumor model in nude mice." (PMID 35184682, 2022). "Knockdown of TARS2 inhibits tumor growth in a xenotransplanted tumor model." (PMID 35184682, 2022). "TARS2 expression in 152 LUAD and 152 paired non-tumor tissues was detected using IHC." (PMID 35184682, 2022). "However, no tumor-related studies of TARS2 have been reported." (PMID 35184682, 2022).
cancer (2 papers, 2011 to 2020). A tumor composed of atypical neoplastic, often pleomorphic cells that invade other tissues. "Possibly, TARS2 possesses unidentified functions beyond tRNA aminoacylation that can also benefit cancer development." (PMID 33266490, 2020).
mitochondrial disease (2 papers, 2014 to 2023). "In conclusion, we identified novel mutations in two genes encoding mitochondrial aminoacyl-tRNA synthetases (VARS2 and TARS2), which have not been appreciated previously as causing mitochondrial disease, thus expanding the list of aaRS2-associated diseases." (PMID 24827421, 2014).
TARS2 also shares sentences with these, for which no sentence is quoted: microcephaly (2 papers); chronic kidney disease (1); gallstones (1); Mitochondrial myopathy (1); neurological disease (1); type 2 diabetes (1).